MIEN1 (migration and invasion enhancer 1)
Description:
Increases cell migration by inducing filopodia formation at the leading edge of migrating cells. Plays a role in regulation of apoptosis, possibly through control of CASP3. May be involved in a redox-related process.
Synonyms: C17orf37; RDX12; XTP4; MGC14832; ORB3; C35
Tractability: Antibody: its Gene Ontology location is reachable by antibodies, with high confidence; UniProt places it where antibodies can reach, with medium confidence; the Human Protein Atlas places it where antibodies can reach. PROTAC: ubiquitination databases record sites on it; its protein half-life has been measured.
Gene: Protein-coding gene on chromosome 17 (39,728,496 to 39,730,555, reverse strand). Ensembl gene ENSG00000141741.
Subcellular location: Cytoplasm, cytosol; Cell membrane
Subcellular location (Human Protein Atlas): Cytosol; Plasma membrane
Gene Ontology:
Molecular function: protein binding
Biological process: negative regulation of apoptotic process; positive regulation of cell migration; positive regulation of filopodium assembly
Cellular component: cytoplasmic side of plasma membrane; cytosol; mitochondrion; plasma membrane
Genetic constraint (gnomAD): Loss-of-function variants: 12 observed, 13.35 expected, observed/expected ratio (o/e) 0.9, 90% interval 0.57 to 1.45. The upper end of that interval is the gene's LOEUF score, 1.45, which puts it in group 6 of 6, group 1 being the genes least tolerant of losing a copy. Missense variants: 160 observed, 135.84 expected, observed/expected ratio (o/e) 1.18, 90% interval 1.03 to 1.34. Synonymous variants: 63 observed, 57.45 expected, observed/expected ratio (o/e) 1.1, 90% interval 0.89 to 1.35.
Homologues: Orthologues: dog MIEN1 (96% identical), pig MIEN1 (96% identical), guinea pig MIEN1 (95% identical), rabbit MIEN1 (95% identical), rat Mien1 (92% identical), mouse Mien1 (90% identical), macaque MIEN1 (77% identical), chimpanzee MIEN1 (77% identical), tropical clawed frog mien1 (63% identical), zebrafish selenow2a (43% identical), zebrafish selenow2b (38% identical), Drosophila melanogaster CG15456 (29% identical). Paralogues in human: SELENOV (25% identical), SELENOW (23% identical).
Diseases named in the same sentence as MIEN1 in open-access papers:
MIEN1 is named in the same sentence as 33 diseases in open-access papers, as found by Europe PMC text mining. Sharing a sentence is not in itself a finding about the gene and the disease. The quoted sentences say what the papers report.
breast carcinoma (30 papers, 2006 to 2025). "Another notable target in breast cancer progression is migration and invasion enhancer 1 (MIEN1), a protein associated with tumor metastasis." (PMID 39845328, 2024). "MIEN1 is known to play a significant part in preserving the plasticity of the dynamic membrane-associated actin cytoskeleton, resulting in a rise in breast cancer cell motility." (PMID 31581708, 2019). "As expected, ITAM phosphorylation was also important for MIEN1-dependent migration and invasion as phospho-deficient MIEN1 mutants severely impaired breast cancer cell migration and invasion." (PMID 26272794, 2015). "MIEN1 expression is positively associated with grade and stage of breast cancer but has low expression in normal tissue." (PMID 23284973, 2012). "The ERBB2, GRB7 and MIEN1 genes, which are located on chromosome 17 in relative proximity within a region including approximately 60,000 base pairs, have been reported co-amplified and associated with poor prognosis in breast cancer." (PMID 28832682, 2017). "It has also been postulated to be a vital marker for EMT and invasiveness in breast cancers with its expression being induced by the MIEN1 gene." (PMID 38272230, 2024). "MIEN1 is known to be a negative regulator of apoptosis and a positive regulator of cell migration and has gained significant interest in its role in breast cancer." (PMID 37762058, 2023). "For example, CDK12 positivity was correlated with HER2 positivity; and MIEN1 overexpression facilitates migration, invasion and metastasis in breast cancer and it is negatively correlated with disease free survival mainly in HER2-positive subtypes." (PMID 37096121, 2023). "Migration and invasion enhancer (MIEN1) are involved in cancer progression and metastasis of breast cancer." (PMID 33926574, 2021). "Expression of MIEN1 in breast cancer cells was arrested after the CRISPR-Cas9 mediated introduction of certain genomic deletions in MIEN1." (PMID 32765953, 2020). "Other studies, such as association of MIEN1 with actin cytoskeletal dynamics, ITAM and AnxA2-mediated metastasis in breast cancer progression have been previously documented." (PMID 31552186, 2019). "MIEN1 expression positively correlates with the grade and stage of breast cancer compared with minimal expression in normal tissues." (PMID 31552186, 2019). "Here we have used the CRISPR-Cas9 system to eliminate MIEN1 protein from breast cancer cells which normally have high MIEN1 expression." (PMID 30286132, 2018). "Here we show that Clustered Regularly Interspaced Short Palindromic Repeat (CRISPR) genome editing effectively produced specific genomic deletions in the MIEN1 gene which led to the abrogation of its expression in breast cancer cells." (PMID 30286132, 2018). "MIEN1 has been shown to functionally increase the invasive and migratory phenotype of various types of cells including breast cancer, prostate cancer, oral cancer, fibroblasts and endothelial cells." (PMID 30286132, 2018). "Due to its proximity to the ERBB2 gene, MIEN1 is commonly amplified in breast cancer along with ERBB2 which leads to an overexpression of MIEN1 protein in many breast cancers." (PMID 30286132, 2018). "Using both wound-healing and chemotaxis-induced migration assays, we assessed the effects of MIEN1 knockdown on breast cancer cell migration." (PMID 27462783, 2016). "In an effort to determine the role of MIEN1 in increased breast cancer cell motility, we first examined the intracellular localization of endogenous MIEN1 in relation to actin filaments by immunostaining." (PMID 27462783, 2016). "Our results demonstrate that modulation of MIEN1 expression leads to the re-organization of actin-rich membrane protrusions in breast cancer cells." (PMID 27462783, 2016). "Here, we demonstrate that MIEN1 acts as a cytoskeletal-signaling adapter protein to drive breast cancer cell migration." (PMID 27462783, 2016).
breast carcinoma (continued). "MIEN1 localization is concentrated underneath the actin-enriched protrusive structures of the migrating breast cancer cells." (PMID 27462783, 2016). "In addition to the prenylation and redox-active motifs, MIEN1 also contains a canonical immunoreceptor tyrosine-based activation motif (ITAM) reported to be associated with epithelial to mesenchymal transition (EMT)-mediated invasion in breast cancer and essential to MIEN1 induced motility." (PMID 27462783, 2016). "Collectively, our data suggest that MIEN1 is an essential signaling adaptor protein in breast cancer cells, which acts through various pathways to control actin rich protrusive structures and adhesion." (PMID 27462783, 2016). "Classification of the patient cohort according to high and low MIEN1 expression using TCGA dataset, confirmed a poor survival in breast cancer patients with elevated MIEN1 expression as previously shown." (PMID 26272794, 2015). "Our studies convincingly demonstrate that interaction of MIEN1 with AnxA2 is required for extracellular plasmin generation thereby increasing breast cancer cell migration and invasion." (PMID 26272794, 2015). "To confirm that MIEN1 regulates AnxA2 dependent plasmin generation, we investigated the effects of MIEN1 ablation either alone or in combination with AnxA2 plasmin generation in breast cancer cells." (PMID 26272794, 2015). "Functional studies confirmed interaction of MIEN1 with AnxA2 at the membrane interface is necessary for activation of plasmin-plasminogen complex, thereby facilitating breast cancer cell migration and invasion." (PMID 26272794, 2015). "Here, we report that MIEN1 regulates breast cancer cell migration and invasion in a bifunctional mechanism." (PMID 26272794, 2015). "To understand the differential expression of MIEN1 in various subtypes of breast cancer, we examined the expression of MIEN1 within the molecular subtypes of breast cancer." (PMID 26272794, 2015). "Using similar knockdown strategy, we observed that dual depletion of MIEN1 and AnxA2 led to a two-fold decrease compared to siGFP, indicating that MIEN1 and AnxA2 functionally cooperate to promote breast cancer cell migration." (PMID 26272794, 2015). "Colocalization experiments using confocal microscopy also confirmed interaction of endogenous AnxA2 and MIEN1 primarily in the cytosol, plasma membrane and the perinuclear area of breast cancer cells." (PMID 26272794, 2015). "MIEN1 has also been predicted as a novel breast cancer biomarker with increased expression in patients with metastatic progression to lung and liver, suggesting its importance in cancer metastasis." (PMID 25406943, 2014). "This approach allows us to deeply understand the role MIEN1 plays in carcinogenesis and tumor progression, which might be transformed in the future as a breast cancer therapeutic option." (PMID 33926574, 2021). "The study illustrated the significance of further research into the specifics of MIEN1-mediated oncogenesis in order to substantiate its prospects as a clinical target and biosignature in breast cancer and how CRISPR could be integral in this process." (PMID 34066014, 2021). "Deletions of MIEN1 gene lead to the abrogation of breast cancer." (PMID 32765953, 2020). "Knocking out MIEN1 in these breast cancer cells will allow future studies to determine the exact role MIEN1 plays in breast tumor metastasis, which might lead to production of novel therapeutics to treat this and other cancers." (PMID 30286132, 2018). "The present study suggests that MIEN1 might be a key cytoskeletal signaling adaptor protein that regulates actin dynamics and cell adhesion during motility in breast cancer." (PMID 27462783, 2016). "Furthermore, treatment of MIEN1 over-expressing cells with Cytochalasin D, which inhibits the binding of G- and F-actin to cofilin, demonstrated that MIEN1 is essential for G-actin to F-actin dynamics in breast cancer cells." (PMID 27462783, 2016).
breast carcinoma (continued). "MIEN1, a novel gene in the 17q12 region of the human chromosome, is not only overexpressed in various solid tumors like oral and ovarian, but also confirmed as a prognosticator in breast cancer." (PMID 27589566, 2016). "Enhanced expression of MIEN1 is reported in breast cancer compared to normal breast tissues." (PMID 26272794, 2015). "MIEN1 expression is significantly increased in breast cancer cells and analysis of TCGA database showed that elevated expression of MIEN1 correlates with poor survival of breast cancer patients." (PMID 26272794, 2015). "Analysis of Cancer Genome Atlas (TCGA) data sets identified significantly elevated MIEN1 expression in different subtypes of breast carcinomas (Apocrine, Large Cell Neuroendocrine, Cribiform, Papillary, Ductal, Lobular, Mixed Ductal and Lobular, Mucinous) patients compared to normal tissues." (PMID 26272794, 2015). "Previous reports indicate that MIEN1 enhances EMT in breast cancer." (PMID 25406943, 2014). "The study indicates that MIEN1 might act as a potential early detection biomarker in breast cancer." (PMID 31552186, 2019). "Moreover, protein expression of MIEN1 was increased in patients with metastasis of breast cancer to lung and liver, which indicates that MIEN1 may be an important mediator of cancer cell metastasis." (PMID 23284973, 2012). "MIEN1 (P < 1 × 10–6 in both secondary screens) is a regulator of cell migration and invasion located near ERBB2 and frequently amplified in HER2-positive breast cancer." (PMID 40165206, 2025). "Migration and invasion enhancer I (MIEN1) and growth factor receptor-bound protein 7 (GRB7) are genes located proximal to the ERBB2 gene and are concomitantly overexpressed in HER2-positive breast cancer subgroups." (PMID 39482530, 2024). "CRISPR/Cas9 has been used to delete the MIEN1 gene in breast cancer models, delivered via cloning vectors such as [pSpCas9(BB)-2A-GFP (PX458)], which successfully silenced MIEN1 expression and inhibited disease progression." (PMID 39845328, 2024). "Migration and invasion enhancer 1 (MIEN1), until recently named C35 or C17orf37, is a novel breast cancer oncogene that is extensively expressed in all types of breast cancers primarily in HER-2 and luminal B subtypes." (PMID 34066014, 2021). "Frequently affected genes by CNVs in Chinese breast cancer patients were ERBB2 (25%), MIEN1 (25%), GRB7 (24%), TRPS1 (6%), MYC (6%), ERLIN2 (6%), PLPP5 (6%), NSD3 (6%), FGFR1 (6%), and CCND1 (5%)." (PMID 33173047, 2020). "The downregulation of MIEN1 suppressed matrix metallopeptidase 9 (MMP9) expression by downregulating Akt expression, indicating that MIEN1 is a prospective molecular target for breast cancer chemotherapy." (PMID 31581708, 2019). "The migration and invasion enhancer 1 (MIEN1/C35/C17orf37) gene is close to the oncogene ERBB2 and has been considered an oncogene in breast cancer." (PMID 31581708, 2019). "MIEN1 is frequently amplified along the neighboring genes, ErBB2 and GRB7 in variety of tumors including breast cancer." (PMID 26272794, 2015). "Additional studies provide evidence for aberrant expression of MIEN1 in different stages of breast cancer with low and/or absence of expression in normal tissues, indicating its development as a potential biomarker." (PMID 31552186, 2019). "Together this data indicates that we have designed highly efficient sgRNAs that are able to efficiently and specifically target the MIEN1 gene and that knocking out MIEN1 does not affect the morphology, growth and survival of breast cancer cells." (PMID 30286132, 2018). "We have confirmed through CRISPR deletion that MIEN1 does not play a role in the proliferation and survival of breast cancer cells, even within 3D culture." (PMID 30286132, 2018). "However, the latest research stated that knockdown of the MIEN1 gene did not alter the morphology, development, proliferation, or survival of breast cancer cells." (PMID 31581708, 2019).
breast carcinoma (continued). "Additionally, MIEN1 promotes cellular adhesion and actin dynamics by inducing phosphorylation of FAK at Tyr-925 and reducing phosphorylation of cofilin at Ser-3, which results in breast cancer cell migration." (PMID 27462783, 2016). "Kaplan-Meier survival analysis showed that the overall survival rate in patients with positive expression of MIEN1 protein was lower than that of those with negative expression of MIEN1 protein; in addition, overexpression of MIEN1 may contribute to the migration and invasion of breast cancer." (PMID 38028542, 2023). "A recent study using a set of eight genes, including MIEN1, revealed a moderate response to adjuvant Trastuzumab therapy even in HER2 negative breast cancer, confirming the importance of this gene in responses to neo-adjuvant therapies." (PMID 25406943, 2014).
prostate carcinoma (12 papers, 2011 to 2023). A carcinoma that arises from epithelial cells of the prostate gland. "Our study indicates that miR-940 expression inversely correlates with tumor progression in clinical prostate cancer and the loss of miR-940 in cancer causes an increased expression of MIEN1 which in turn enables prostate cancer progression." (PMID 25406943, 2014). "On the one hand, MIEN1 diminishes the PCa cell migration, and on the other hand, it increases the epithelial cell polarity in the prostate cancer cells." (PMID 36839985, 2023). "The migration and invasion enhancer 1 (MIEN1) gene, which is highly expressed in prostate cancer cells, regulates AKT/NF-κB signaling." (PMID 33050597, 2020). "In this research, we identified the MIEN1 expression levels in prostate carcinoma cells and normal prostate tissues and examined the potential functions and regulatory mechanisms of downstream MIEN1 target genes in prostate carcinoma cells." (PMID 31581708, 2019). "MIEN1 also can affect NDRG1 gene expression in prostate carcinoma cells via the Akt signal pathways." (PMID 31581708, 2019). "In prostate cancer, MIEN1 is overexpressed in the higher grades of prostate adenocarcinoma compared with low expression in normal or benign prostatic tissue." (PMID 31552186, 2019). "Further study indicated that hypomethylation of the SINE Alu region of the MIEN1 promoter and upstream stimulatory factor 1 (USF1) binding triggered MIEN1 expression in prostate cancer in vitro and in vivo." (PMID 31581708, 2019). "Our study is the first report indicating NF-κB-modulated gene expression of MIEN1 in human prostate carcinoma cells." (PMID 31581708, 2019). "Our research collectively showed that MIEN1 not only increased in vitro and in vivo cell growth but also exhibited anti-apoptotic effects in cells of prostate carcinoma." (PMID 31581708, 2019). "The present study revealed that overexpression of MIEN1 enhanced the invasion and migration ability of prostate carcinoma cells." (PMID 31581708, 2019). "The reporter assays showed that transient-cotransfected MIEN1 expression vector decreased the reporter activity of NDRG1 reporter vector in prostate carcinoma PC-3 and LNCaP cells." (PMID 31581708, 2019). "The study demonstrated high expression of MIEN1 in prostate cancer cell lines and tumors in comparison to normal tissues (low expression)." (PMID 31552186, 2019). "Collectively, knockdown of MIEN1 attenuated the cell proliferation and tumorigenesis of prostate carcinoma cells." (PMID 31581708, 2019). "In prostate carcinoma cells, MIEN1 provoked Akt phosphorylation; moreover, MIEN1 downregulated N-myc downstream regulated 1 (NDRG1) but upregulated interleukin-6 (IL-6) gene expression." (PMID 31581708, 2019). "Our study showed that overexpression of MIEN1 enhanced resistance to cisplatin-induced apoptosis and cell viability in prostate carcinoma PC-3 cells." (PMID 31581708, 2019). "Our findings suggest that MIEN1 is an oncogene in prostate cancer, and this is consistent with our prior research." (PMID 31581708, 2019). "A previous study disclosed that MIEN1 was expressed in the cytosol with intense staining in the membrane of prostate carcinoma cells, and it functionally enhanced migration and invasion via NF-κB/Akt activity." (PMID 31581708, 2019). "In this study, the sequence analysis of the putative MIEN1 promoter region in immortalized normal epithelial cells and prostate cancer cells reveal a pattern of hypomethylation of the SINE Alu segment in cancer cells." (PMID 27589566, 2016). "In conclusion, this study is the first to identify methylation as an important modulator of MIEN1 in prostate cancer progression." (PMID 27589566, 2016). "Migration and invasion enhancer 1 (MIEN1) is a novel gene involved in prostate cancer progression by enhancing prostate cancer cell migration and invasion." (PMID 27589566, 2016).